CD34 (CD34 molecule)
Diseases named in the same sentence as CD34 in open-access papers (continued):
Sharing a sentence is not in itself a finding about the gene and the disease.
latent infection (62 papers, 2010 to 2025). "After primary infection, CMV causes a latent infection and resides in cells of the myeloid compartment (CD34+, monocytes)." (PMID 38674675, 2024). "HCMV has been shown to manipulate the secretion of cellular proteins during both lytic and latent infection; with changes caused by latent infection mainly investigated in CD34+ progenitor cells." (PMID 33912186, 2021). "As reported in CD34+ latent infection, the CD14+ latency-associated secretome also suppressed the anti-viral activity of stimulated CD4+ T cells." (PMID 33912186, 2021). "It has been reported that pUL138 encoded by the UL133-UL138 polycistronic locus promotes latent infection in primary CD34+ hematopoietic progenitor cells (HPCs) infected in vitro." (PMID 32481657, 2020). "During latent infection, viral gene expression in CD34+ cells is highly restricted and associated with secretion of immunomodulatory cytokines cIL-10 and TGFβ." (PMID 24130479, 2013). "Recently, it has been shown that CD34+ progenitor cells (that include HSCs and MPPs) are susceptible to latent infection ex vivo, and that integrated provirus was detected among CD34+ cells from HAART-treated patients." (PMID 23364195, 2013). "We have previously identified sequences in the ULb′ region of the HCMV genome encoding the UL138 protein (pUL138) that are required for a latent infection in CD34+ hematopoietic progenitor cells (HPCs) infected in vitro." (PMID 22241980, 2011). "Recent evidence indicates that a subset of the 22 HCMV-encoded miRNAs are expressed during latent infection of CD34+ HPCs (19, –, 21), suggesting that these viral gene products play important roles in latency establishment and maintenance, as well as in sensing signals for viral reactivation." (PMID 33824207, 2021). "Herein, we investigated the role of HCMV UL78 in latent infection of human embryonic stem cell (hESC) -derived CD34+ HPCs." (PMID 40501644, 2025). "Utilizing primary- and hESC-derived CD34+ HPCs, we show that recombinant viruses with mutations in the ICL3 region of US28 fail to efficiently reactivate from latent infection." (PMID 39655954, 2025). "The virus establishes a lifelong latent infection in CD34+ haematopoietic stem and progenitor cells (HSPCs) and myeloid lineage cells within the human host, typically remaining asymptomatic unless immune surveillance is compromised." (PMID 40872823, 2025). "Human cytomegalovirus (HCMV) is a ubiquitous betaherpesvirus that establishes lifelong latent infection in CD34+ haematopoietic stem and progenitor cells." (PMID 40872823, 2025). "The removal of the productively infected GFP+ cells allowed for a more accurate experimental analysis of latent infection in CD34+ cells in the subsequent experiments." (PMID 40872823, 2025). "The activation of the STING pathway upstream of p-IRF3 during latent infection in CD34+ cells suggests the activation of DNA sensors." (PMID 40872823, 2025). "In this study, we first compared CD34+ cells that supported productive and latent infections using the RV-TB40-BACKL7-SE-EGFP virus." (PMID 40872823, 2025). "To further examine how latent infection affects the dynamics of the CD34+ subsets, we analysed their frequencies over time in the HCMVGFP− cells." (PMID 40872823, 2025). "By utilising the RV-TB40-BACKL7-SE-EGFP virus, we can distinguish between CD34+ cells that support productive infection and those that support latent infection." (PMID 40872823, 2025). "Primary infection is typically asymptomatic and results in the establishment of latent infection within CD34+hematopoietic progenitor cells (HPCs)." (PMID 39655954, 2025). "Human CMV (HCMV) achieves persistence in part through the ability to establish latent infections in CD34+ hematopoietic progenitor cells (HPCs) and CD14+ monocytes." (PMID 40501644, 2025). "To this end, we conducted proximity-dependent labeling experiments in CD34+ HPCs stimulated to reactivate from latent infection." (PMID 40501644, 2025).
latent infection (continued). "It is believed that CMV latent infection exists in early myeloid cells, particularly CD34+ hematopoietic stem cells, which can be reactivated to infect parenchymal cells of various organs." (PMID 38561696, 2024). "Human cytomegalovirus (HCMV) is a species-specific virus that establishes a persistent/latent infection in CD34+ hematopoietic progenitor cells (HPCs)." (PMID 37772824, 2023). "Carter and colleagues showed latent infection of Lin-CD34+CD133+CD38- primitive HSPC subsets in vitro and corroborated these findings with bone marrow CD34+ HSPCs from HIV infected individuals with high viral load." (PMID 37497228, 2023). "It was reported previously that CMV can establish a latent infection in CD34+ hematopoietic progenitor cells of individuals with a competent immune system, and it was undetectable by the host immune system due to the low level of viral antigen." (PMID 36409152, 2022). "Previously, we have shown that experimental latent infection of CD34+ progenitor cells alters the cellular secretome to induce migration of CD4+ T cells and subsequent suppression of their effector function." (PMID 33912186, 2021). "Our data suggest that HCMV miR-US25-1 is important for limiting proliferation of infected CD34+ HPCs during latent infection in order to enrich for genome-containing cells." (PMID 33824207, 2021). "Akt is activated rapidly following latent infection of monocytes and CD34+ HPCs, though it is attenuated by 72hpi in monocytes and minimally sustained in CD34+ HPCs." (PMID 34663377, 2021). "We started by checking that latent infection of undifferentiated WT-iPSCs induced TGFbeta, as we have previously observed for CD34+ progenitors cells." (PMID 34061599, 2021). "The virus can establish a latent infection in CD34+ hematopoietic progenitor cells (HPCs) and periodically reactivate to cause disease in the absence of an intact immune system." (PMID 33408225, 2021). "CD133+ cells had a higher propensity to recover the virus than CD34+ cells did, suggesting a potential phenotype for latent infection." (PMID 33981874, 2021). "US28 expression during latent-infection of CD34+ HPCs plays a key role in the maintenance of latency." (PMID 32850474, 2020). "To determine if our newly generated US28 stop mutant displayed a similar phenotype during latent infection, we infected Kasumi-3 and cord blood-derived CD34+ cells with wt or stopUS28 for 7d under latent conditions." (PMID 32411622, 2020). "Although UL146 and UL147 are expressed with late kinetics during lytic infection, recent evidence suggests that both genes are also expressed at low levels during latent infection of CD34+ progenitor cells." (PMID 33096622, 2020). "UL138 has also been found to affect surface levels of Epidermal Growth Factor Receptor (EGFR), with increased signaling activity enhancing latent infection of CD34+ myeloid progenitor cells." (PMID 33096622, 2020). "Four novel proteins, namely pUL133, pUL135, pUL136, and pUL138, have been shown to be encoded by the UL133-UL138 locus, and it has been reported that pUL138 promotes a latent infection in primary CD34+ HPCs infected in vitro." (PMID 32481657, 2020). "In fibroblasts and endothelial/epithelial cells viral particles are produced via a lytic replication cycle, but in CD34+ hematopoietic stem cells (HPCs), the virus establishes a latent infection." (PMID 32850474, 2020). "Lifelong latent infections are established in CD34+progenitor cells in the bone marrow, which are hallmarked by a lack of major lytic gene expression, genome replication and virus production." (PMID 32375946, 2020). "EGFR and downstream PI3K signaling are important for establishing and maintaining a latent infection in CD34+ HPCs." (PMID 31725809, 2019). "Despite this, HCMV is not cleared from the host but persists by establishing a lifelong latent infection in undifferentiated cells of the myeloid lineage (CD34+ haematopoietic progenitor cells and their derivative CD14+ monocytes)." (PMID 31580403, 2019).
latent infection (continued). "Since HCMV latent infection of CD34+ HPCs results in decreased myeloid colony formation, and expression of EGR-1 is a major determinant in the proliferative capacity of progenitor cells, we examined the direct effects of miR-US22 on myelopoiesis." (PMID 31725809, 2019). "HCMV can establish latent infection in early myeloid lineage cells, including CD34+ progenitor cells and CD14+ monocytes, the former of which comprise the major cell type present in HSCTs." (PMID 31580403, 2019). "Our own interests lie in the mechanisms HCMV utilises to establish latent infections of CD34+ progenitor cells." (PMID 29547547, 2018). "Further, monocytes can travel directly to the bone marrow and infect CD34+ hematopoietic stem cells, a major latency reservoir, establishing a life-long latent infection." (PMID 30127257, 2018). "Human cytomegalovirus (HCMV) establishes a lifelong latent infection of the hematopoietic CD34+ cell population resident in the bone marrow and persists in the cells of the myelo-monocytic cell lineage." (PMID 30021158, 2018). "Loss of UL138 results in a virus that is unable to establish or maintain a latent infection in CD34+ HPCs and instead replicates productively." (PMID 27218650, 2016). "We know that latent infection of primary CD34+ progenitor cells by HCMV results in their increased survival in the face of pro-apoptotic signals, and this, at least in part, appears to involve the known latency-associated increase in the expression of cIL-10." (PMID 25772624, 2015). "One of the cellular miRNAs which is known to be downregulated during latent infection of CD34+ progenitor cells is hsa-miR-92a." (PMID 25772624, 2015). "Consistent with this, and the known increase in cIL-10 during HCMV latent infection of CD34+ cells, latently infected CD34+ cells also showed extensive increases in STAT3 phosphorylation and concomitant increases in the expression of Bcl2 and HSP70." (PMID 25772624, 2015). "The extent to which latent infection of CD34+ cells, in itself, drives the latently infected progenitor cell down the myeloid lineage, rather than the lymphocyte lineage, is unclear." (PMID 25772624, 2015). "Conversely, in certain cell types, such as undifferentiated monocytes and their CD34+ progenitors, latent infection can be established." (PMID 25253336, 2014). "For HCMV latent infection of CD34 (+) cells we harvested RNA at 11 days post infection and the RNA-Seq peak map shows the presence of the same transcripts detected in latently infected CD14 (+) cells (11 day latent)." (PMID 23717203, 2013). "Following primary infection, HCMV establishes a latent infection of the CD34+ haematopoietic cell population in the bone marrow." (PMID 24284875, 2013). "Disruption of the UL133-UL138 locus resulted in a virus, UL133-UL138NULL, with increased frequency of infectious centers formation in CD34+ HPCs relative to the wild-type virus, consistent with a failure to establish a latent infection." (PMID 22241980, 2011). "Recently, it has also been proposed that other viruses such as HTLV-1 and Kaposi's Sarcoma Herpesvirus (KSHV) can also infect CD34+ HP/HSCs and establish latent infection within the BM resident cells." (PMID 20132553, 2010). "Our data demonstrate that latent infection alters the differentiation state of CD34+ cells." (PMID 40872823, 2025). "Since an observed deficit in viral reactivation can be caused by an inability to maintain viral genomes or genome-containing cells throughout latency, we quantified viral genome copies from infected CD34+ HPCs at the end of latent infection via quantitative PCR." (PMID 40501644, 2025). "Human cytomegalovirus (HCMV) remains a significant cause of morbidity and mortality after solid organ transplant and hematopoietic stem cell transplant due to the ability of the virus to establish a latent infection in CD34+ hematopoietic progenitor cells (HPCs) (3, –, 5)." (PMID 37772824, 2023).
latent infection (continued). "We hypothesized that HCMV protects the lytically infected cell from the effects of TGFβ signaling by manipulating components of the TGFβ signaling pathway, as we have observed during latent infection in CD34+ HPCs." (PMID 34411201, 2021). "Cmv-miR-UL22A targets SMAD3 to prevent robust TGFβ signaling during latent infection of CD34+ HPCs." (PMID 34663377, 2021). "Thus, cmv-miR-UL148-mediated regulation of the IER5-CDC25B axis is important for latent infection of Kasumi-3 and primary CD34+ cells." (PMID 34663377, 2021). "HCMV establishes a latent infection in CD34+ progenitor cells and CD14+ monocytes." (PMID 34290252, 2021). "We recovered virus from CD133+ as well as from CD34+ cells, suggesting the establishment of latent infection in these specific cells, which could potentially confer vertical transmission and reactivation of the virus." (PMID 33981874, 2021). "Indeed, the upregulation of cIL-10 during latent infection in both CD34 and CD14 monocytes has been proposed to play an antiapoptotic role in latently infected cells." (PMID 32582563, 2020). "Infected monocytes are a vector for viral spread due to their mobility and ability to migrate into most organ tissues, and it is the infiltration of infected monocytes into the bone marrow that is required for the establishment of latent infection in the CD34+ HPC reservoir." (PMID 32850474, 2020). "This includes understanding the subtle signaling differences in the various latency models, such as monocytes versus dendritic cells versus CD34+ HPCs, and how these may change over time during latent infection." (PMID 30127257, 2018). "Thus the virus activates a pathway to promote entry of CD34+ cells but then must express viral gene products to inactivate EGFR signalling post-entry to establish a latent infection." (PMID 29547547, 2018). "We next characterized the virus during latent infection of CD34+ cells." (PMID 30021158, 2018). "However, this powerful signal activation appears to contrast with the recently identified requirement for US28 expression to establish a latent infection in CD34+ stem cells, likely by repressing viral IE gene expression." (PMID 29208743, 2017). "Here, we first determined whether the NR-1 clinical strain can achieve latent infection in CD34+ hematopoietic progenitor cells (HPCs) and Kasumi-3 cells." (PMID 27824944, 2016). "Also, consistent with previous analyses using primary CD34+ cells, latent infection of Kasumi-3 cells resulted in their protection from FAS-mediated killing (lane 5)." (PMID 25957098, 2015). "In addition to the regulation of secreted proteins during latency, an apoptome array shows that there are also a number of changes in levels of anti-apoptotic proteins during latent infection of CD34+ cells with HCMV." (PMID 25772624, 2015). "It is well established that HCMV establishes a latent infection in CD34+ hematopoietic progenitor cells, and recent studies indicate that persistence is maintained, in part, through HCMV-induced generation of CD4+ T cells that secrete cIL-10 in response to HCMV antigens." (PMID 25794555, 2015). "Hence these data show that there are common transcripts associated with HCMV latent infection in both CD14 (+) and CD34 (+) cells, including two lncRNAs and mRNAs that encode UL84 and UL44." (PMID 23717203, 2013). "During latent infection expression of viral UL111A (vIL-10) results in down regulation of MHC class II and diminished CD4+ T cell recognition and latent infection of CD34+ bone marrow progenitor cells induces release of cIL-10 and TGFβ which decreases CD4+ T cell IFNγ production and cytotoxicity." (PMID 24130479, 2013). "Given the role of pUL138 in latency, the other proteins expressed from the UL133-UL138 locus may function to cooperate with pUL138 in establishing a latent infection in CD34+ cells." (PMID 22241980, 2011).
latent infection (continued). "Latent genomes either from in vitro infected CD34+ cells or from natural latent infections in vivo display unacetylated and H3K9 dimethylated histones and are associated with the HP-1 transcriptional repressor, similar to what is found during lytic infection in the absence of pp71." (PMID 21429246, 2011). "It has been hypothesized that HTLV-1 can specifically induce a latent infection in CD34+ HP/HSCs and can initiate preleukemic events in these progenitor cells." (PMID 20132553, 2010). "To determine whether UL78 has a role in the establishment of latent infection or the capacity of the virus to reactivate, we infected human embryonic stem cell (hESC)-derived CD34+ HPCs with either WT-HCMV (TB40/E-GFP) or UL78–2XSTOP (TB40/E-GFP-UL78-2XSTOP) viruses." (PMID 40501644, 2025). "To assess whether loss of genomes could explain the reactivation defect observed with either of the recombinant viruses containing ICL3 mutations, we quantified viral genome copies from infected hESC-derived CD34+ HPCs at the beginning and end of latent infection via quantitative PCR." (PMID 39655954, 2025). "Interestingly, our previous analyses have shown that hsa-miR-29a is decreased during latent HCMV infection of CD34+ cells 1.5-fold, suggesting that latent infection may help maintain levels of YY1, although levels of YY1 were never assessed in that analysis." (PMID 34061599, 2021). "Indeed, latent infection of Kasumi-3 cells results in all the hallmarks of latent infection observed in primary CD34+ cells, such as maintenance of the viral genome with concomitant lack of lytic IE72 expression but the presence of expression of the latency-associated LUNA gene." (PMID 25957098, 2015). "Infected CD34+ HPCs were isolated via FACS and cultured above a murine stromal support layer under conditions that favor latent infection." (PMID 39655954, 2025). "In both primary and hESC-derived CD34+ HPCs infected with HCMV HB-K223A or HCMV HB-R225A, we observed deficits in the ability of the virus to efficiently reactivate from latent infection when compared with wild-type-infected cells." (PMID 39655954, 2025). "In order to successfully establish a latent infection, HCMV must enter CD34+ HPCs, maintain its genome, and simultaneously support essential cellular functions to avoid cell death and detection by the innate and adaptive immune responses." (PMID 33668486, 2021). "To determine how EGR1 is regulated during CMV latent infection, we analyzed EGR1 mRNA expression in TB40/E-infected CD34+ HPCs derived from two donors at 2 and 6 dpi by RNA sequencing." (PMID 31725811, 2019). "One of the most abundantly expressed viral miRNA we observed during latent infection was miR-UL148D; this was expressed in both latently infected monocytes and CD34+ cells." (PMID 27491954, 2016). "THY-1 is expressed in many types of cells that can be productively infected by HCMV as well as CD34+/CD38- stem cells, a putative cellular reservoir for latent infection." (PMID 26147640, 2015). "Cis and trans acting factors involved in human cytomegalovirus experimental and natural latent infection of CD14 (+) monocytes and CD34 (+) cells." (PMID 24603756, 2014). "CD14 (+) or CD34 (+) cells cultured in vitro can be infected with HCMV clinical strains, resulting in latent infection and efficient reactivation of latent virus." (PMID 23717203, 2013). "The parameters involved in human cytomegalovirus (HCMV) latent infection in CD14 (+) and CD34 (+) cells remain poorly identified." (PMID 23717203, 2013). "Collectively, these results indicate that UL78 – Gαi coupling is not required for the establishment of viral latency in CD34+ HPCs but is required for efficient reactivation from latent infection." (PMID 40501644, 2025). "While miR-US22 is not detected during latent infection of CD34+ HPCs, it is thought to be re-expressed following reactivation when viral gene expression is re-initiated." (PMID 33668486, 2021).